SPARC (secreted protein acidic and cysteine rich)
Diseases named in the same sentence as SPARC in open-access papers (continued):
Sharing a sentence is not in itself a finding about the gene and the disease.
breast carcinoma (continued). "In this context, expression of SPARC was found to inhibit epithelial cell proliferation, in part through stimulation of TGFβ signaling, while in MCF7 breast carcinoma cells expressing oncogenes, SPARC induced cell motility and aggressiveness." (PMID 23441215, 2013). "These included genes such as SCUBE3, MARCKSL1 and PGK1 in lung cancer, SOX4 and GNAS in breast cancer and hepatocellular carcinoma, HEG1 in hepatocellular carcinoma, PLS3 in pancreatic adenocarcinoma, FBN1 and SPARC in gastric cancer and CST1 in gastric cancer and breast cancer." (PMID 40430098, 2025). "Therefore, before constructing the TAAs-derived peptides expressing rVACV, we evaluated the expression of the SPARC protein and MHC class I molecules H2-Kd and H2-Ld in mammary cancer cell lines 4T1 and N2C by western blot analysis and flow cytometry." (PMID 41050655, 2025). "SPARC-mediated degradation of the ECM and its potential link to MMPs could lead to breast cancer development." (PMID 37577749, 2023). "STABILIN-1 has also been proposed to be a scavenger receptor important for the clearance of extracellular tumor growth-inhibiting molecules, such as SPARC or chitinase-like protein, from the TME in some tumor types (breast cancer and neuroblastoma), thereby leading to tumor growth." (PMID 36230610, 2022). "SPARC is positively related with TNM staging and histological grade of breast cancer patients." (PMID 35211625, 2022). "While low stromal PTEN expression has previously been observed in breast cancer patients, changes in SPARC expression in the stroma of human breast tumors had not been investigated." (PMID 33534863, 2021). "Cath-D and SPARC expression in TNBC was examined using an online transcriptomic survival analysis, tissue micro-arrays, TNBC cell lines, patient-derived xenografts (PDX), human TNBC samples, and mammary tumors from MMTV-PyMT Ctsd-/-knock-out mice." (PMID 33995652, 2021). "SPARC was cleaved in the conditioned medium from this mouse mammary cancer cell line at pH 5.5 only in the absence of OH-Tam." (PMID 33995652, 2021). "In addition to SNAIL1 effects, LOXL2 influences expression of SPARC and the extracellular proteins TIMP1 and MMP9; in fact, LOXL2 was noted as prognostic factor in breast cancer." (PMID 28425924, 2017). "Intraperitoneal injection of SPARC did not significantly increase lung tumor nodules in an intravenous metastasis model, just as was found in breast cancer cells." (PMID 28969021, 2017). "Previous studies have indicated that SPARC promotes bone metastasis and epithelial-mesenchymal transition (EMT) in some types of highly metastatic cancers, including melanoma, prostate cancer, and breast cancer." (PMID 28969021, 2017). "Moreover, we observed a positive correlation of the mRNA levels between RUNX2 and BRGs (ITGBL1, SPARC and POSTN) in primary breast cancer tissues." (PMID 27806311, 2016). "The aim of this study was to determine the changes in a panel of stromal proteins within the tumor, including THBS1, TNC, FN, SPARC and α-SMA, following neoadjuvant chemotherapy in newly diagnosed breast cancer patients using immunohistochemistry (IHC) staining." (PMID 27487140, 2016). "Supporting this idea, breast cancer lung metastases overexpressing SPARC require SPARC to promote invasion, but overexpressing SPARC is not sufficient to drive metastasis." (PMID 26926673, 2016). "Certainly, the highest plasma levels of SPARC were those of the patients who did not develop metastasis, and who showed variable positivity for SPARC (from + to ++, n = 3) in the breast carcinoma tissue (see representative images of fields for Patient 5)." (PMID 26703564, 2015). "Consistently, primary breast carcinoma that did not give bone metastasis abundantly release SPARC in the plasma, likely preventing, therefore, the engraftment of disseminated cells in the secondary bone site." (PMID 26703564, 2015).
breast carcinoma (continued). "The reduction in cell migration and metastatic potential exhibited by these pancreatic cell lines following SPARC knockdown suggests that it may contribute to CTC-mediated metastasis, consistent with prior work in breast cancer models." (PMID 25242334, 2014). "The role of SPARC in the development and progression of breast cancer is still not fully elucidated." (PMID 20687958, 2010). "Furthermore, four other candidate genes SPARC, THY1, IL1B and CXCL8 are reported in this study as the key regulatory genes which can modulate co-regulatory between different clusters in the PPI network of the brain metastasis tumours from breast cancers." (PMID 35045088, 2022). "Some examples are oncostatin M, able to restrain mammary cancer cell growth in vitro, fatigue substance (F-Substance) isolated from muscles of trained rats and displaying inhibitory effect on the breast cancer cell line MCF-7 and secreted protein acidic and rich in cysteine (SPARC)." (PMID 30984014, 2019). "With respect to molecular mechanistic studies of Cu proteins’ roles in breast cancer, there is such information reported for ten proteins and below we discuss findings for selected proteins of the ten (MEMO1, SPARC, LOX, and some LOX-like proteins), followed by a separate section about ATOX1." (PMID 28425924, 2017). "However, when the SPARC inhibition threshold induced by Maitake is overcome, breast cancer will be developed without SPARC control." (PMID 27401257, 2016). "There is little evidence of SPARC's effect in breast cancer patients, especially in TNBC." (PMID 27421134, 2016). "Notably, the plasma level of SPARC was not elevated in breast cancer patients with bone metastasis outcome." (PMID 26703564, 2015). "For example, a strong cytoplasmic SPARC expression was found in stromal cells surrounding malignant tissues in breast cancer, but was absent in stromal cells of normal breast tissues, and SPARC expression in the surrounding stromal of breast cancer was significantly higher than tumor cells." (PMID 20565704, 2010). "Loss of SPARC in PMN-MDSCs resulted in reduced tumour growth in two subcutaneous breast cancer models and isolation of splenic PMN-MDSCs from wild-type and SPARC−/− mouse spleens demonstrated that those lacking SPARC were unable to suppress T-cell activation." (PMID 33187209, 2020). "Previous studies have shown that SRPX2 and SPARC were overexpressed in gastric cancer tissues, while TLN2 was upregulated in breast carcinomas tissues; however, no studies investigating the expression of TLN2, SRPX2, and SPARC in peripheral blood have been reported." (PMID 23548070, 2013).
melanoma (85 papers, 2003 to 2025). A malignant, usually aggressive tumor composed of atypical, neoplastic melanocytes. "The increased expression of the SPARC gene in human melanoma is associated with epithelial-to-mesenchymal transition (EMT), which is a major determinant of metastasis in melanoma patients." (PMID 40943659, 2025). "In certain cancers, such as melanomas, the expression of SPARC has been associated with clinical outcomes and metastasis development." (PMID 40943659, 2025). "Since gene activity is precisely coordinated to execute cellular functions, we carried out gene set enrichment analysis (GSEA) to identify signaling and cellular pathways associated with SPARC in melanoma progression." (PMID 40943659, 2025). "Our study also demonstrates that the expression levels of both HDAC10 and SPARC respond to the activity state of mutated BRAF in melanoma cells." (PMID 38650694, 2024). "For example, increased SPARC expression is strongly associated with tumor progression in gliomas and melanomas, while some studies have reported SPARC as a tumor suppressor in neuroblastomas as well as ovarian and colorectal cancers." (PMID 39424639, 2024). "HDAC10 and SPARC are implicated in chemotherapy response across different types of cancer, but their roles in BRAFi resistance in melanoma are unexplored." (PMID 38650694, 2024). "While HDAC10 depletion caused a significant SPARC upregulation in melanoma cells, SPARC expressions in lung cancer cells were too low to effectively gauge any change brought about by HDAC10 depletion." (PMID 38650694, 2024). "Our work indicates that the growth inhibition of melanoma cells is closely linked to SPARC upregulation following stable HDAC10 depletion." (PMID 38650694, 2024). "Accordantly, highly expressed and exogenous SPARC displayed an increased susceptibility of melanomas to the growth-inhibitory impact of drugs like cisplatin." (PMID 38650694, 2024). "In melanomas and gliomas, enhanced SPARC expression associates with a highly aggressive tumor phenotype, whereas in pancreatic adenocarcinoma, acute myeloid leukemia, and ovarian and colorectal carcinomas, SPARC behaves as a tumor suppressive molecule." (PMID 34199373, 2021). "The lack of SPARC expression in CRC is a poor prognostic factor whereas high SPARC expression in breast, melanoma, and gastric cancers is associated with worse outcomes." (PMID 29623263, 2018). "SPARC overexpression was associated with highly aggressive human melanomas and its secreted fraction underlies the communication between tumor cells and surrounding microenvironment." (PMID 29484133, 2018). "Activation of the PI3K/Akt pathway by SPARC promotes melanoma cell invasion and survival advantages linked to a worse prognosis." (PMID 26248315, 2015). "Exposing SPARC-deficient cells to a dominant negative form of Rac1 promoted cells’ transition to a more aggressive phenotype that resembled control melanoma cells." (PMID 26248315, 2015). "This is consistent with the abrogated in vivo tumorigenic capacity of SPARC-deficient melanoma cells." (PMID 26248315, 2015). "Our results show SPARC/AKT-dependent regulation of SLUG as an important mechanism underlying EMT-induced cell migration in melanoma." (PMID 22911700, 2012). "One mechanism underlying SPARC function in melanoma appears to be E-cadherin repression and promotion of an EMT-like transition, a process having a central role during RGP to VGP progression." (PMID 22911700, 2012). "Although the melanoma sample size analyzed here is relatively small, the results indicate that SPARC and SLUG expression is positively associated during melanoma progression, further underlining the importance of our present observations." (PMID 22911700, 2012).
melanoma (continued). "SPARC expression is associated with aggressive invasion and metastasis in prostate cancer, glioma, and melanoma cells." (PMID 22481923, 2012). "In certain types of cancers, such as melanomas and gliomas, SPARC is associated with a highly aggressive tumour phenotype." (PMID 19920824, 2010). "SPARC is a stromal cell protein associated with melanoma invasiveness." (PMID 37577749, 2023). "In addition, SPARC expression was associated with melanoma progression in nude mice, and with poor clinical outcome in human small melanoma lesions." (PMID 37762344, 2023). "The cellular origin of SPARC protein also seems important for its function, as specifically stromal SPARC is associated with tumor progression in pancreatic cancer, while tumor-derived SPARC increased vascular permeability in melanoma." (PMID 29176937, 2017). "In glioma and melanoma, the metastatic capacity is associated with SPARC expression." (PMID 28718842, 2017). "An increase in cell size was associated with a delay in the G1/S phase; interestingly, SPARC-deficient melanoma cells exhibited a delay in S phase entry suggesting a clear link between the downregulation of SPARC levels, increase in cells’ size and cycling arrest." (PMID 26248315, 2015). "SPARC is a highly conserved matricellular glycoprotein whose expression has been associated with aggressive, mesenchymal-like phenotypes in a variety of human cancers, including melanoma." (PMID 26248315, 2015). "Last, Osteonectin (secreted protein acidic and rich in cysteine (SPARC)), which has been implicated in metastasis of melanoma to the lungs, and PlagL1 (Pleomorphic adenoma gene-like 1), a potential tumor suppressor gene, were also overexpressed in DC-tumor fusions." (PMID 26605345, 2015). "SPARC has been reported to function as a tumor suppressor in neuroblastoma, breast, pancreatic, lung and ovarian cancers, yet SPARC is associated with highly aggressive tumor phenotypes in melanomas and gliomas." (PMID 23648148, 2013). "Furthermore, the in vivo depletion of PMN was able to reverse tumorigenesis of SPARC-deficient melanoma cells, suggesting that SPARC can inhibit the recruitment of PMN to the tumor environment." (PMID 22481923, 2012). "In addition, high SPARC expression was associated with poor prognosis and survival in colorectal cancer, melanoma and oesophageal cancer." (PMID 15558074, 2004). "In some cancers, such as melanomas and gliomas, SPARC is associated with a highly aggressive tumor phenotype, while in others, mainly ovarian cancer, neuroblastoma and colorectal cancer, SPARC may function as a tumor suppressor." (PMID 24213109, 2011). "For example, in certain types of cancers, such as melanomas and gliomas, SPARC is associated with a highly aggressive tumor phenotype, while in others, mainly in neuroblastomas, as well as in ovarian and colorectal cancers, SPARC functions as a tumor suppressor." (PMID 20687958, 2010). "Thus, in certain types of cancers, such as melanomas and gliomas, SPARC is associated with a highly aggressive tumour phenotype, whereas in others, mainly ovarian, neuroblastomas, and colorectal cancers, SPARC may function as a tumour suppressor." (PMID 19920824, 2010). "In melanoma cells and colorectal cancer cells, exogenous addition of SPARC significantly inhibited the cell proliferation and enhanced chemosensitivity of tumor cells that had become resistant to chemotherapy when compared with those tumor cells that were deficient in endogenous SPARC." (PMID 20565704, 2010). "In conclusion, we propose a PRRX1/TCF7L2-Sp1/miR-29 regulatory axis, which involves Wnt/β-catenin and MAPK signaling pathways, as a key mechanism controlling SPARC expression in melanoma." (PMID 40943659, 2025). "Herein, we show that SPARC expression in melanoma cells relies on transcriptional activation by PRRX1/TCF7L2-Sp1 and post-transcriptional regulation by miR-29b1~a." (PMID 40943659, 2025).
melanoma (continued). "To complement the study, we aimed to compare SPARC expression levels between the recently defined phenotypic melanoma states." (PMID 40943659, 2025). "Misregulation of miR-29 family members has been reported in melanoma and has been demonstrated to profoundly impact tumor initiation, growth, and invasion by targeting genes other than SPARC." (PMID 40943659, 2025). "Currently, interest in SPARC is growing as its expression levels in melanoma tumors show good predictive value for anticipating the emergence of chemoresistance to BRAF/MEK-inhibitor therapies." (PMID 40943659, 2025). "Firstly, we corroborated previous studies and found that levels of SPARC mRNA and protein in clinical samples and melanoma cell lines correlate with progression." (PMID 40943659, 2025). "We also show that SPARC is a target of the miR-29 family, whose members are expressed in clinical melanoma samples and cell lines." (PMID 40943659, 2025). "Together, our work suggests that PRRX1 expression, β-catenin/TCFL2, c-Jun, and Sp1 converge to achieve maximal SPARC promoter activity in melanoma cells." (PMID 40943659, 2025). "Its action is accompanied by an increase in TCF7L2, a cofactor of β-catenin, which was also found to be enriched in the SPARC promoter in invasive melanoma cells." (PMID 40943659, 2025). "We selected a panel of melanoma cell lines, harboring either mutated or wild type NRAS/BRAF genes, to investigate SPARC promoter activity." (PMID 40943659, 2025). "In this study, we propose a PRRX1/TCF7L2-Sp1/miR-29 regulatory axis, which involve Wnt/β-catenin and MAPK signaling pathways to regulate SPARC expression in melanoma." (PMID 40943659, 2025). "Accordingly, we found that Sp1 was significantly enriched in the SPARC promoter region (−175 to −25 nt relative to the TIS) in melanoma cell lines as determined by chromatin immunoprecipitation, but not in the IgG controls." (PMID 40943659, 2025). "We found that inhibition by either UO126 or PD98059 inhibitors diminished SPARC protein levels in all melanoma cell lines." (PMID 40943659, 2025). "Collectively, these results indicate that PRRX1 acts as a transcriptional activator of the SPARC gene in melanoma cells, promoting its expression." (PMID 40943659, 2025). "In conclusion, the study highlights the role of the PRRX1/TCF7L2-Sp1/miR-29b1~a signaling axis in regulating SPARC expression in melanoma." (PMID 40943659, 2025). "The expression of the Secreted Protein, Acidic and Rich in Cysteine (SPARC) gene in human melanoma increases during disease progression and is strongly associated with EMT, a major determinant of metastasis in melanoma patients." (PMID 40943659, 2025). "Herein, we identified the transcriptional factors and signaling pathways responsible for the constitutive expression of the SPARC promoter, as well as those that provide maximal activation, in invasive melanoma cells." (PMID 40943659, 2025). "Taken together, SPARC expression in melanoma cells relies on transcriptional activation by PRRX1/TCF7L2-Sp1 and is modulated through miR-29b1~a, which provides fine-tuning regulation over the switch between phenotypic states." (PMID 40943659, 2025). "The phenotypic switch between melanoma states is a dynamic and reversible process, during which SPARC has variable levels of expression." (PMID 40943659, 2025). "miR-29 targeting SPARC has been detected in cancer, but its regulatory function in SPARC expression in melanoma remains elusive." (PMID 40943659, 2025). "Overall, Sp1 motifs were enriched at PRRX1-binding sites in WM 793-expressing cells, suggesting a cooperative role between PRRX1 and Sp1 in the transcriptional activation of the SPARC gene in melanoma cells." (PMID 40943659, 2025). "It has been well known for years that SPARC is upregulated throughout melanoma progression, playing crucial roles in this process by inducing EMT and promoting metastatic development." (PMID 40943659, 2025).